USP30-AS1 (USP30 antisense RNA 1)
Gene: Long non-coding RNA gene on chromosome 12 (109,051,572 to 109,054,008, reverse strand). Ensembl gene ENSG00000256262.
Diseases named in the same sentence as USP30-AS1 in open-access papers:
USP30-AS1 is named in the same sentence as 1 disease in open-access papers, as found by Europe PMC text mining. Sharing a sentence is not in itself a finding about the gene and the disease.
USP30-AS1 shares sentences with these, for which no sentence is quoted: bacterial infection (1 paper).